CD4 (CD4 molecule)
Diseases named in the same sentence as CD4 in open-access papers (continued):
Sharing a sentence is not in itself a finding about the gene and the disease.
infection (continued). "Since our data indicates at 60 days post-infection in old SDR mice there is increased IL-10 mRNA levels in the lungs, we next examined whether CD4+ T cells in the lungs of these mice have the phenotype of IL-10 producing regulatory T cells." (PMID 36189368, 2022). "Interestingly, we found that STM ΔchiA infection leads to a significant increase in the CD4+ and CD25+ T cells, as well as the double-positive CD4+CD25+ T cell population." (PMID 35482710, 2022). "These HIV-specific CD4+ and CD8+ T cells could be sorted and sequenced in hyperacute infections and/or HIV exposed but seronegative individuals and compared to ART treated individuals or elite controllers to assess transcriptomic differences." (PMID 35972938, 2022). "Regarding CM T lymphocytes, there were no significant alterations in this population after infection for CD4+ and CD8+ T cells." (PMID 35720410, 2022). "Besides infection, though, vaccine-induced CD8+ T cell responses are also significantly lower than their CD4+ counterparts." (PMID 35813877, 2022). "It was observed that during the initial days of infection (Day 1), CD8+ T cells had a greater reduction in frequencies than CD4+ T cells, which happened for neither less severe patients nor in later day points since the infection." (PMID 36248882, 2022). "CD8+ and CD4+ T cells comprised of 40% and 10% of CD45+ cells in BAL after VACV∆C7L infection." (PMID 35351885, 2022). "When the frequency of CD4+ T cells producing IFN-γ was compared, similarly, there was a significant increase in the blood (P<0.01), LN (P<0.01), and spleens (P<0.05) of WT rats following infection with S. japonicum." (PMID 35584107, 2022). "Although similar frequencies of CTLA‐4+CD4+FoxP3+ regulatory cells (TREG) were found between groups, CTLA‐4 expression in this compartment was twice as high in symptomatic compared to asymptomatic infection." (PMID 35475529, 2022). "Interestingly, LCMV induced a marked decrease in similarity in both V gene and amino acid motif usage in both CD4+ and CD8+ naive repertoires, perhaps reflecting increased turnover and perturbation of this compartment in response to the infection." (PMID 35967295, 2022). "On the other hand, we previously demonstrated that at later post-stimulation time points (48 h), either infection with Ba or stimulation with its RNA inhibit the expression of MHC-II and MHC-I in monocytes/macrophages and the consequent antigen presentation to CD4+ and CD8+ T cells, respectively." (PMID 36441810, 2022). "After 3 days of culture to establish infection, the HIV-infected PBMCs, CD4+ T cells, or monocytes (1 × 105 cells/well) were either left untreated or treated with added autologous UTD T cells or anti-HIV duoCAR effector T cells (effector/target [E:T] ratio of 1:1)." (PMID 36345941, 2022). "A few studies have assessed memory CD4+ T cells and CD8+ T cells at least 6 months after infection." (PMID 34975340, 2022). "We found that even in the absence of IFN-γ signaling, CD4 T cells drive macrophage activation, M1 polarization, and control of infection." (PMID 35877763, 2022). "CD4 T cell control of HCMV spread in APC has been described, and we wanted to understand whether the spread of infections can be similarly restricted in other relevant cell types." (PMID 36445084, 2022). "Moreover, multifunctional CD4+ T cells, which are correlated to the defensive immune response, were shown to be higher in LTB infection than active TB disease and were inversely correlated with reduced bacterial load." (PMID 35056035, 2022). "We report here that virus cell-to-cell transfer through cell-cell fusion with infected CD4+ T cells is a very effective means of infecting MΦ, even with virus isolates characterized as non-macrophage tropic in cell-free infection." (PMID 35622876, 2022).
infection (continued). "Here we found that increased plasma concentrations of IL-10, MCP-1, IL-1rα, IL-2, IL-6 and SCGFβ had a negative impact on CD4:CD8 ratio during acute infection (< 180 days post infection), as evaluated by linear regression model." (PMID 35165387, 2022). "Mice depleted of both CD4 and CD8 T cells showed a marked increase in susceptibility to infection, while mice lacking either CD4 or CD8 T cells still controled and cleared bacteria." (PMID 35693783, 2022). "When regarding SARS-Cov/SARS-Cov2 CD4+ and CD8+ T cells, the memory T cell response is maintained for at least 4–6 years after infection in 70%–100% of patients, and is partially correlated with the infection severity." (PMID 35434592, 2022). "However, some subsets of CD4 T cells have been shown to promote the HSV disease and infection in mice." (PMID 35277184, 2022). "Regarding the lymphocyte markers, the transcription of the T cells, tcrb, and cd8a was down-regulated during infection in both the gills and in the HK, whilst the marker cd4 was not altered." (PMID 35055122, 2022). "Although potentially reflecting differences in the chronology and/or context of antigen exposure, these results suggest that ancestral SARS-CoV-2 spike-specific CD4+ and CD8+ T cells elicited by natural infection provide comprehensive but relatively incomplete coverage against B.1.1.529." (PMID 35042228, 2022). "CD4+ T cells are a critical component of effective immune responses tovaricella zoster virus (VZV), but their functional properties during thereactivation acute vs latent phase of infection remain poorly defined." (PMID 36865570, 2022). "In contrast, CD4+ T cells target structural proteins of the virus i.e., capsid, envelope and secreted NS1 proteins, which are responsible for the production of memory T cells at the late stage of infection." (PMID 35215836, 2022). "However, at day 30 after infection, the frequency of ESAT-6-specific IFN-γ-producing CD4+ T cells in the lungs of both unvaccinated B6 and pMT-10 mice were higher than in vaccinated B6 and pMT-10 mice." (PMID 35935958, 2022). "HIV-1 RNA at baseline was higher in patients with non-B than in those with subtype B infections, despite slightly higher CD4+ T cell counts." (PMID 36312730, 2022). "HIV/SIV has also been found to infect astrocytes during acute infection, which express little to no CD4, supporting the infection of other immune cell types in the brain." (PMID 36146803, 2022). "Instead, the OPC susceptibility in Aire-deficient mice was driven by the overproduction of interferon-γ (IFN-γ) by oral mucosal CD4+ and CD8+ T cells, which were both necessary and sufficient to promote infection in this setting via disrupting the oral epithelial barrier." (PMID 34964702, 2022). "Tregs (CD4+CD25+CD127lo) were also found to be significantly decreased in those who that developed an infection (21.0 cells/μL) versus those that did not (42.0 cells/μL) and HCs (50.0 cells/μL)." (PMID 35958579, 2022). "The degree of control of HCMV Merlin GFP infections by CD4 T cells in the absence of the anti-IL-10 block indicates T cell capacities that remain functional, despite the presence of induced IL-10 and pUL11." (PMID 36445084, 2022). "It has now been fully established that vaccine induced CD4 and CD8 T cells residing at the respiratory mucosa plays a critical role in pulmonary immunity to pathogens by immediately encaging the pathogens at the site of infection." (PMID 35757753, 2022). "The notable changes in the earliest T cell events post-infection at the time of peak viral loads in BAL (1-2dpi following aerosol or IN/IT exposure) with opposing patterns between circulating Vδ1T cells and CD4 T cells were further demonstrated by tSNE plots from flow cytometric analyses." (PMID 36526890, 2022).
infection (continued). "In order to further explore the role of neutrophils in DC mediated Th1 cell polarization in vivo, we also measured mRNA levels of T-bet, a lineage marker of Th1 cell differentiation, in CD4+ T cells from ear dLNs of GL113 or 1A8 treated LdWT and LdCen-/- infected mice 5d post infection." (PMID 35192633, 2022). "However, emerging data indicate that SARS-CoV-2 vaccination diversifies the CD4+ S-reactive T cell repertoire in patients with prior SARS-CoV-2 infection or vaccine breakthrough infection with omicron." (PMID 36389833, 2022). "Using adoptive T cell transfer, we demonstrated that Y-specific CD4+ T cells and Y- and PS-specific CD8+ T cells provided significant protection against a lethal infection with TMUV Y, indicating a crucial role of T cells in the protective immune response to TMUV." (PMID 36016955, 2022). "HIV induces death of tissue CD4 T cells through two principal mechanisms:1) productive infection of activated cells followed by non-inflammatory apoptosis and 2) abortive infection of nonpermissive cells leading to inflammatory pyroptosis." (PMID 35784348, 2022). "There were statistically significant increases in CD3+CD4+ and CD3+CD8+ lymphocytes upon infection." (PMID 35614490, 2022). "Since EECA countries have adopted a “treat-all” and “treat-early” policy regardless of CD4 cell count and stage of infection, ART coverage has steadily increased over the past decade." (PMID 35061671, 2022). "Similarly, PD-1+CD4+ and PD-1+CD8+ T cells were also increased in the splenocytes, and peritoneal cells (PECs) isolated from IFN-I treated mice with PRU infection." (PMID 36214572, 2022). "Interestingly, later events were comparable between MAVS deficient and wt mice, and there were no major differences in immune cell (neutrophils, inflammatory monocytes, CD4+ and CD8+ T cells) recruitment to the lungs from day 2–9 post primary infection." (PMID 35108347, 2022). "Consistent with our prior data in general geriatric populations, our cohort of WNV‐exposed participants exhibited significantly lower levels of circulating CD8, but not CD4, Tn cells when compared individuals who experienced asymptomatic infection." (PMID 35289071, 2022). "Comparison of the frequencies of CXCR3+ cells as a fraction of non-naïve (CD95+) CD8+ and CD4+ T cells over time provided further evidence of more efficient homing of T cells to the site of infection in the younger animals." (PMID 35039442, 2022). "Similar to their inbred counterparts, outbred SPexp mice had increased proinflammatory cytokines (IL-2, IL-6, TNF-α, and IFN-γ), decreased cellularity in the blood, and an increased frequency of Ag-experienced CD4 and CD8 T cells within PBL 5 d after last infection, as seen in inbred SPexp mice." (PMID 35878936, 2022). "The frequencies of CD4+ and CD8+ T cells and dendritic cells (DCs) in coinfected mice dramatically decreased, while the frequencies of NKG2D+ cells among CD8+ T cells increased at 7 days post LCMV Arm infection." (PMID 35672321, 2022). "Unexpectedly, some CD4 reactivity towards M protein was observed in vaccinated healthy donors and oncologic patients, who did not reportedly have a previous infection." (PMID 36139625, 2022). "In children, no changes in CD38/HLA-DR co-expression on CD4+ T cells were found between different time points after infection." (PMID 35197982, 2022). "We also found CCR5‐tropic infection occurred in vitro in phenotypically naïve cells when CD4+ T cells were infected in bulk, but not when naïve cells were pre‐sorted and then infected." (PMID 35916394, 2022). "Compared with that in the infection-only and hybrid-immunity groups (7–12 months post vaccination), the proportion of SARS-CoV-2-specific CD4+ T cells in the hybrid-immunity group within 6 months post vaccination was 1.65-fold (P < 0.05) and 1.28-fold higher, respectively." (PMID 36494338, 2022).
infection (continued). "However, we also showed that a significant number of these cells, in particular CD4+ cells, co-express GATA-3 with T-bet in the steady state and during infection." (PMID 36159876, 2022). "In contrast, CD11c+T-bethi B cells were depleted in CD4cre/+ x Adora2aflox/flox mice that had been treated with CGS-21680 from days 30–37 post-infection, indicating that depletion of CD11c+T-bethi B cells did not require A2A receptor signaling on CD4+ T cells." (PMID 35064115, 2022). "As seen with MDMs, the X4 T-tropic Env virus showed no infectivity, demonstrating that pMGL lack the CD4 densities necessary for efficient infection by this virus." (PMID 35975998, 2022). "The same pattern was seen in both groups of sows (without transplacental infection: 40.8 ± 13.3% in CD4 SP and 44.3 ± 20.0% in CD4/CD8α DP; with transplacental infection 41.5 ± 15.9% and 47.0 ± 11.8% respectively; non-significant)." (PMID 36798517, 2022). "Abortive infection and pyroptotic cell death affect non-permissive CD4 T cells, also called “bystander” T cells, which die from HIV intrusion even though they do not sustain a productive infection." (PMID 35784348, 2022). "Spike-specific T cells have been found in SARS-CoV-2 patients, including in mild disease, and 30–50% of healthy people without infection were found to have SARS-Cov2 specific CD4+ and CD8+ cytotoxic T cells, possibly HCoV cross-reactive T cells." (PMID 35192617, 2022). "Furthermore, a prior asymptomatic infection had a comparable impact on the frequency of CD4+ T cell, cTFH cell, and CD8+ T cell memory following vaccination compared to the enhancement seen with prior symptomatic infection." (PMID 36168391, 2022). "predicted that CD4+ and CD8+ T-cell memory has a half-life of 3-5 months but may reach a more stable plateau 8 months after infection, or the decline in such memory may slow down over time." (PMID 36389144, 2022). "Those with a baseline CD4 <350 were reclassified as ‘not late’ if they had evidence of recent infection (recency test and/or negative test within 24 months)." (PMID 36069144, 2022). "Whereas most HIV-producing cells are eradicated by the immune system in the early phase of infection, small pools of non-activated or naïve infected CD4+ T and T memory cells persist, still containing proviruses." (PMID 35202165, 2022). "Finally, we observed that a massive clonal expansion occurred within CD4-CTL IFNhigh and CTL IFNlow clusters, in both CUN and COV groups, suggesting a probable active role of these cells in controlling the infection." (PMID 35710943, 2022). "Of note, the infection of mixed-bone marrow chimeras revealed that wild-type (WT) but not Myd88-/- cells transcribe the CD4CTL gene signature and that Il18ra-/- and Myd88-/- CD4+ T cells phenocopy each other." (PMID 35670567, 2022). "Infection of monocytes and/or macrophages by HIV may also increase the turnover of mature cells, in a manner similar to CD4 T cells, and lead to lower numbers of circulating monocytes as they surge to replace end-stage tissue macrophages." (PMID 35546661, 2022). "A study demonstrated that infection by HIV-1 of hMDMs or CD4+ lymphocytes does not induce IFN production or results in a very modest IFN response (low levels of IFN after several days post-infection)." (PMID 35458396, 2022). "Expression of Notch1 on IFNγ+CD4+T cells revealed an increase between days 7 and 14 of infection in lungs but not LNs." (PMID 35603470, 2022). "However, in infected adults, slightly higher frequencies of CD4+ TEM and CD8+ TEM cell subsets were found at later time points after infection." (PMID 35197982, 2022). "To examine the longevity of the SARS-CoV-2 induced T-cell responses, we analyzed how the CD4+ and CD8+ T-cell responses changed over time from diagnosis of infection (samples collected up to 259 days from diagnosis) in 90 paired samples collected from the same individuals." (PMID 36068292, 2022).
infection (continued). "This contrasts natural infection of mice that fails to lodge CD4+ Trm cells along the respiratory tract or provide protection against re-infection, despite initially generating Th17 bacterium specific CD4+ T cell responses." (PMID 35637249, 2022). "Collectively, these data show that primary infection with S. aureus fails to evoke protective immunity and this correlates with an impairment in the persistence of S. aureus specific memory CD4+ T cells along the airways." (PMID 35637249, 2022). "Nevertheless, IL-12 cytokine is not required for the activation of MDSCs in the biofilm infection since MDSCs from both p35 knockout, and IL-12 p40 mice still inhibit the proliferation of CD4+ T cells." (PMID 35093033, 2022). "One of the most important roles of the DC during an infection is their ability to upregulate MHC class II and costimulatory molecules in order to provide a strong signal 1 and 2, priming and costimulation, respectively, to CD4 T cells." (PMID 36119079, 2022). "However, by week 4, in line with the increased bacterial replication seen at this time point, total number of CD4+ T cells in Mtb-LT1 infected mice rose significantly and was higher than that in Mtb-HT1 infection." (PMID 35173157, 2022). "These two human respiratory pathogens generate distinct profiles of antigen-specific CD4+ and CD8+ T-cell responses upon infection, which potentially can contribute to the different levels of protection against re-infection with antigenically evolved viruses that escape from antibody immunity." (PMID 36146622, 2022). "Activated CD44+ CD4 T cells initially expanded in the ILN and could be detected infiltrating the FRT during the first week of infection." (PMID 35196366, 2022). "This can explain why low levels of CCR5 expression on CD4+ T cells in natural hosts does not reduce the infection of the CD4+ T cells, permit high viremia, and result in infection of cells with short lifespan in natural host in comparison to non-natural host." (PMID 35154162, 2022). "Thus, R5 clade C strains maintain a preference for infecting memory CD4+ T-cells during later stages of infection, whereas emergent X4 HIV-1 clade C strains preferentially target TN CD4+ T-cells." (PMID 34668779, 2022). "During a co-infection model with St, where IFN-γ contributes to survival and IFN-γ+ CD4+ T cells do not reach their numerical peak until the third week of infection, IL-10 is detrimental in the second week of infection." (PMID 35631044, 2022). "In addition, there is an increase in activated CD4+ and CD36+ T cells and macrophages during the first stages of infection, followed by an increase in IFN-γ, TNF-α, and NO in spleen cells." (PMID 35682626, 2022). "When compared to the uninfected controls, the frequency of human CD4+ T cells in the vaginal mucosa, spleen and lung, and CD68+ macrophages in lung tissue of both the huNRG and huDRAG-A2 mice was significantly reduced at 8 weeks post-infection." (PMID 36146734, 2022). "As UEA1 binds α1–2 branched fucose, these results suggest that fucosylation is globally upregulated upon infection of tissue CD4+ T cells with HIV, although not the type of fucosylation that creates α1–2 branched structure." (PMID 35787792, 2022). "Absence of CCR5 expression on naive CD4 cells has been suggested as mechanism of resistance against direct infection of these cells." (PMID 35794176, 2022). "Resistance was further increased after blocking of type 1 cytokines early during infection, whereas IFN-γ supplementation during priming of the CD4+ T cell response selectively promoted the outgrowth of Th2/1 hybrid cells, resulting in the impaired control of nematode fitness." (PMID 35690651, 2022). "We have previously reported significant CD4+, B, and T-cell proliferative responses in sheep vaccinated with Gudair® that were not protected against infection." (PMID 36504842, 2022).